DDRGK1 (DDRGK domain containing 1)
Description:
Component of the UFM1 ribosome E3 ligase (UREL) complex, a multiprotein complex that catalyzes ufmylation of endoplasmic reticulum-docked proteins. The UREL complex plays a key role in ribosome recycling by mediating mono-ufmylation of the RPL26/uL24 subunit of the 60S ribosome following ribosome dissociation: ufmylation weakens the junction between post-termination 60S subunits and SEC61 translocons, promoting release and recycling of the large ribosomal subunit from the endoplasmic reticulum membrane. Ufmylation of RPL26/uL24 and subsequent 60S ribosome recycling either take place after normal termination of translation or after ribosome stalling during cotranslational translocation at the endoplasmic reticulum. Within the UREL complex, DDRGK1 tethers the complex to the endoplasmic reticulum membrane to restrict its activity to endoplasmic reticulum-docked ribosomes and acts as an ufmylation 'reader': following RPL26/uL24 ufmylation, DDRGK1 specifically binds to ufmylated RPL26/uL24 via its UFIM motif, resulting in stable association between the 60S ribosome and the UREL complex, followed by dissociation of the 60S ribosome subunit from the endoplasmic reticulum membrane. The UREL complex is also involved in reticulophagy in response to endoplasmic reticulum stress by promoting ufmylation of proteins such as CYB5R3 and RPN1, thereby promoting lysosomal degradation of ufmylated proteins. Ufmylation-dependent reticulophagy inhibits the unfolded protein response (UPR) by regulating ERN1/IRE1-alpha stability. Acts as a regulator of immunity by promoting differentiation of B-cells into plasma cells: acts by promoting expansion of the endoplasmic reticulum and regulating the unfolded protein response (UPR) (By similarity). May also be required for TRIP4 ufmylation. May play a role in NF-kappa-B-mediated transcription through regulation of the phosphorylation and the degradation of NFKBIA, the inhibitor of NF-kappa-B. Plays a role in cartilage development through SOX9, inhibiting the ubiquitin-mediated proteasomal degradation of this transcriptional regulator. Required for stabilization and ufmylation of ATG9A (By similarity).
Synonyms: C20orf116; UFBP1; dJ1187M17.3; SEMDSH
Tractability: Antibody: UniProt predicts a signal peptide or a membrane-spanning region. PROTAC: UniProt records ubiquitination sites on it; ubiquitination databases record sites on it; its protein half-life has been measured.
Gene: Protein-coding gene on chromosome 20 (3,188,734 to 3,204,700, reverse strand). Ensembl gene ENSG00000198171.
Subcellular location: Endoplasmic reticulum membrane
Subcellular location (Human Protein Atlas): Endoplasmic reticulum; Nucleoli
Pathways (Reactome):
Signal Transduction: RHOA GTPase cycle
Gene Ontology:
Molecular function: protein binding; ubiquitin-like protein ligase binding; UFM1-modified protein reader activity
Biological process: cartilage development; negative regulation of gene expression; negative regulation of IRE1-mediated unfolded protein response; negative regulation of proteasomal ubiquitin-dependent protein catabolic process; positive regulation of canonical NF-kappaB signal transduction; positive regulation of cell migration; positive regulation of cell population proliferation; positive regulation of gene expression; positive regulation of I-kappaB phosphorylation; positive regulation of proteasomal protein catabolic process; positive regulation of proteasomal ubiquitin-dependent protein catabolic process; positive regulation of protein catabolic process; positive regulation of reticulophagy; positive regulation of transcription by RNA polymerase II; protein K69-linked ufmylation; protein localization to endoplasmic reticulum; protein ufmylation; regulation of intracellular estrogen receptor signaling pathway; regulation of protein stability; rescue of stalled ribosome; response to endoplasmic reticulum stress; reticulophagy; ribosome disassembly; negative regulation of apoptotic process; negative regulation of PERK-mediated unfolded protein response; and 3 more
Cellular component: endoplasmic reticulum; endoplasmic reticulum membrane; transferase complex; cytoplasm
Genetic constraint (gnomAD): Loss-of-function variants: 38 observed, 41.08 expected, observed/expected ratio (o/e) 0.93, 90% interval 0.71 to 1.21. The upper end of that interval is the gene's LOEUF score, 1.21, which puts it in group 5 of 6, group 1 being the genes least tolerant of losing a copy. Missense variants: 403 observed, 395.7 expected, observed/expected ratio (o/e) 1.02, 90% interval 0.94 to 1.11. Synonymous variants: 171 observed, 158.84 expected, observed/expected ratio (o/e) 1.08, 90% interval 0.95 to 1.22.
Homologues: Orthologues: chimpanzee DDRGK1 (99% identical), macaque DDRGK1 (96% identical), pig DDRGK1 (90% identical), dog DDRGK1 (90% identical), rabbit DDRGK1 (89% identical), rat Ddrgk1 (85% identical), mouse Ddrgk1 (84% identical), guinea pig DDRGK1 (70% identical), tropical clawed frog paip2b (61% identical), Drosophila melanogaster Ddrgk1 (41% identical), Caenorhabditis elegans ufbp-1 (35% identical).
Diseases named in the same sentence as DDRGK1 in open-access papers:
DDRGK1 is named in the same sentence as 51 diseases in open-access papers, as found by Europe PMC text mining. Sharing a sentence is not in itself a finding about the gene and the disease. The quoted sentences say what the papers report.
diabetes (4 papers, 2021 to 2024). "Recently, a study reported that DDRGK1 maintained the stability of IRE1α 7, and increasing evidence has shown that decreased DDRGK1-induced ER stress is associated with a variety of diseases, including cancer, neurodegeneration, diabetes, and proinflammatory diseases 14-18." (PMID 37781516, 2023). "Absence of DDRGK1 leads to significant levels of endoplasmic reticulum (ER) stress and causes a range of conditions, such as malignancies, neurodegenerative disorders, diabetes, and inflammatory disorders." (PMID 39022342, 2024).
gastric cancer (4 papers, 2019 to 2024). A primary or metastatic malignant neoplasm involving the stomach. "Another study showed that low expression of CDK5RAP3 and DDRGK1 are related to poor prognosis in patients with gastric cancer." (PMID 31528213, 2019).
Obesity (4 papers, 2021 to 2026). Accumulation of substantial excess body fat. "Our work elucidates the adipocyte-specific DDRGK1-UFMylation-FASN axis as a novel therapeutic target for obesity-associated metabolic dysfunction." (PMID 41671397, 2026).
osteosarcoma (3 papers, 2021 to 2025). A usually aggressive malignant bone-forming mesenchymal neoplasm, predominantly affecting adolescents and young adults. "Research on osteosarcoma treatment has revealed that DDRGK domain-containing protein 1 (DDRGK1) inhibits the ubiquitin-proteasome-mediated degradation of NRF2 by competitively binding to Keap1." (PMID 40258841, 2025). "Indeed, DDRGK1 knockout significantly enhances osteosarcoma chemosensitivity to DOX in vivo." (PMID 36965071, 2023). "Taken together, these results reveal a crucial role of DDRGK1 in the KEAP1/NRF2/ROS pathway, which contributes to osteosarcoma development and chemoresistance." (PMID 36965071, 2023).
anemia (2 papers, 2015 to 2021). A reduction in the number of red blood cells, the amount of hemoglobin, and/or the volume of packed red blood cells. "Inducible deletion of UFL1 or UFBP1 (also known as DDRGK1) in adult mice causes severe anemia." (PMID 34722315, 2021).
Hip dysplasia (2 papers, 2021). The presence of developmental dysplasia of the hip. "Continuing with this theme, familial dominant mutations in the UFSP2 or DDRGK1 gene resulted in Beukes and Sohat hip dysplasia, with loss of DDRGK1 function abolishing SOX9 mediated transcription of type II collagen." (PMID 33578803, 2021).
non-alcoholic fatty liver disease (2 papers, 2023 to 2024). "Similarly, in nonalcoholic fatty liver disease in mice, there’s an upregulation of DDRGK1, UFM1, and UFM1-conjugated DDRGK1, contributing to increased UFMylation expression." (PMID 38233375, 2024).
acute kidney injury (1 paper, 2024). Sudden and sustained deterioration of the kidney function characterized by decreased glomerular filtration rate, increased serum creatinine or oliguria. "Our study further corroborates these findings, showing a reduction in DDRGK1, UFL1, and UFM1 in acute kidney injury, which suggests a decrease in ER-phagy." (PMID 38233375, 2024).
glioma (1 paper, 2024). A benign or malignant brain and spinal cord tumor that arises from glial cells (astrocytes, oligodendrocytes, ependymal cells). "The first three pathways (glycine serine and threonine metabolism, base excision repair, etc.)of DDRGK1 were enriched in the high expression group, while the remaining 17 pathways (such as inositol phosphate metabolism and glioma) were enriched in the low expression group." (PMID 39022342, 2024).
Parkinson disease (1 paper, 2024). A progressive degenerative disorder of the central nervous system characterized by loss of dopamine producing neurons in the substantia nigra and the presence of Lewy bodies in the substantia nigra and locus coeruleus. "GSEA analysis demonstrated significant associations between HIPK2 and DDRGK1 with ribosome, Parkinson’s disease, oxidative phosphorylation, and other pathways." (PMID 39022342, 2024).
spondyloepiphyseal dysplasia (1 paper, 2023). An osteochondrodysplasia that results in abnormalities of bone growth in the vertebral column and the epiphysis. "Spondyloepiphyseal dysplasia (SEMD) is a rare disease in which cartilage growth is disrupted, and the DDRGK1 mutation is one of the causative genes." (PMID 37781516, 2023).
cancer (10 papers, 2017 to 2024). A tumor composed of atypical neoplastic, often pleomorphic cells that invade other tissues. "Previous studies have shown that DDRGK1 regulates the stability of IRE1α in several types of cancer cells, such as MCF-7 and HepG2 cells." (PMID 37781516, 2023). "Consistent with in vitro studies in cancer cell lines, our in vivo results indicate that DDRGK1 is critical for the survival of HSCs, as knockdown of DDRGK1 leads to elevated ER stress and apoptosis in HSCs." (PMID 28128204, 2017). "We demonstrate that depletion of DDRGK1 induces ER stress and enhances ER stress-induced apoptosis in both cancer cells and HSCs." (PMID 28128204, 2017). "Here, we show that depletion of DDRGK1 induces ER stress and enhances ER stress-induced apoptosis in both cancer cells and hematopoietic stem cells (HSCs)." (PMID 28128204, 2017). "The activation of apoptotic genes like PDCD6, associated with apoptotic signalling cascades, and DDRGK1, implicated in DNA repair and apoptosis, suggests that fig latex triggers apoptosis pathways, leading to cell death specifically in HPV-positive cancer cells." (PMID 38139849, 2023). "DDRGK1 knockout attenuates NRF2 stability, contributing to ROS accumulation, which promotes apoptosis and enhanced chemosensitivity to doxorubicin (DOX) and etoposide in cancer cells." (PMID 36965071, 2023). "The absence of DDRGK1 correlated with ROS accumulation and enhanced chemosensitivity to DOX and etoposide in OS cancer cells." (PMID 36965071, 2023).
tumor (6 papers, 2015 to 2025). "Tumor growth was significantly reduced in DOX‐treated DDRGK1 knockout mice compared to that in wild‐type mice, indicating a promising novel clinical strategy for OS treatment." (PMID 36965071, 2023). "Bioinformatic and tissue analyses indicate that higher expression of DDRGK1 correlates with advanced tumor stage and poor clinical prognosis of OS." (PMID 36965071, 2023). "DDRGK1 knockout significantly decreased OS growth rate in terms of tumor size and weight when compared to control mice." (PMID 36965071, 2023). "DOX led to concomitant dose‐dependent cellular death and a decrease in the half‐maximal inhibitory concentration (IC50) in DDRGK1 knockout cells, suggesting that DDRGK1 knockout enhances tumor sensitivity to DOX." (PMID 36965071, 2023). "In addition, DDRGK1 expression correlated with the Tumor Node Metastasis (TNM) stage." (PMID 36965071, 2023).
DDRGK1 also shares sentences with these, for which no sentence is quoted: fatty liver (4 papers); chronic hepatitis C (3); liver fibrosis (3); Pancytopenia (3); breast carcinoma (2); colitis (2); schizophrenia (2); spondyloepimetaphyseal dysplasia (2); acute myeloblastic leukemia (1); acute promyelocytic leukemia (1); alcoholic hepatitis (1); atherosclerosis (1); Cirrhosis (1); colon cancer (1); corneal dystrophy (1); dyslipidemia (1); heart failure (1); hepatocellular carcinoma (1); hyperlipidemia (1); hypertriglyceridemia (1); infection (1); Insulin resistance (1); insulinoma (1); ischemic heart diseases (1); liver disease (1); lung adenocarcinoma (1); lung carcinoma (1); microcephaly (1); myeloid leukemia (1); neurodegenerative disease (1).
A further 8 diseases each share a sentence with DDRGK1 in 1 paper.